OSMR (oncostatin M receptor)
Diseases named in the same sentence as OSMR in open-access papers (continued):
Sharing a sentence is not in itself a finding about the gene and the disease.
retinopathy (2 papers, 2016 to 2017). "As a first next step, we would suggest to treat OSMR deficient mice with STZ and measure vasoregression as relevant early time point in retinopathy." (PMID 28575111, 2017). "Taken together with these reports, our findings support a role for EP300 as a key modulator of the anti-apoptotic effects of the endogenously activated STAT1/3–IL6ST/OSMR axis in light-induced retinopathy." (PMID 27242532, 2016). "Collectively, these findings are consistent with the possibility that STAT1/3–IL6ST/OSMR axis may be activated in light-induced retinopathy as an endogenous anti-apoptotic signaling pathway." (PMID 27242532, 2016). "Therefore, the retinopathy-associated increase in IL6ST and OSMR detected here may be a result of STAT1/3-mediated transcriptional activation." (PMID 27242532, 2016).
digestive system cancer (1 paper, 2025). A primary or metastatic malignant neoplasm involving any part of the digestive system. "After comparing the co-expressed genes in these five digestive system cancers, five genes, PKD2, CDH11, OSMR, ITGB1, and BNC2, were further identified as being associated and interacting with ITGAV through the Venn diagram." (PMID 40018050, 2025).
OSMR also shares sentences with these, for which no sentence is quoted: aortic stenosis (2 papers); cardiomyopathies (2); colitis (2); mastitis (2); myocardial infarction (2); pancreatic cancer (2); pancreatic ductal adenocarcinoma (2); acute myeloblastic leukemia (1); bladder squamous cell carcinoma (1); cardiac sarcoidosis (1); Cerebral ischemia (1); cholangiocarcinoma (1); diabetic cardiomyopathy (1); dyslipidemia (1); esophageal carcinoma (1); Ewing sarcoma (1); familial primary localized cutaneous amyloidosis (1); hematological malignancies (1); hyperprolactinemia (1); hypertrophy (1); lung adenocarcinoma (1); lung carcinoma (1); lymph node metastasis (1); mesothelioma (1); metastatic cancers (1); myeloproliferative neoplasm (1); osteoarthritis (1); osteoporosis (1); pancreatic adenocarcinoma (1); primary liver cancers (1).
A further 8 diseases each share a sentence with OSMR in 1 paper.